DLL4 (delta like canonical Notch ligand 4)
Diseases named in the same sentence as DLL4 in open-access papers (continued):
Sharing a sentence is not in itself a finding about the gene and the disease.
cancer (continued). "Targeting Dll4 is considered one of the new anti-cancer therapy." (PMID 26766040, 2016). "In the future, these results could help refine anti-cancer treatments that work by blocking the activity of Vegfa and Dll4." (PMID 27074663, 2016). "Elevated Dll4 expression predicts poor prognosis in different cancers." (PMID 26314892, 2015). "Although these findings indicate that the Dll4/Notch blockade may provide an effective way to improve cancer control, the capacity for normalization of the aberrant vascular network to Dll4/Notch inhibition remains undetermined." (PMID 26314892, 2015). "Importantly, the DLL4/Notch/Hey1/MMP9 cascades connecting the endothelium to the cancer cells in metastasis were identified." (PMID 24931473, 2014). "This supports the notion that further strategy in anti-cancer therapy could be based on Dll4/Notch signaling blockade." (PMID 23967403, 2013). "Experimentally, DLL4 expression in cancer cells has been previously analyzed." (PMID 23898884, 2013). "Therefore, to more accurately evaluate DLL4 function, its expression must be examined in both the peritumoral vasculature and cancer cells." (PMID 23898884, 2013). "With our increasing understanding of the function of this pathway in both normal cell fate decisions and in cancer, anti-DLL4 may become the prototype member of a new class of therapeutic agents." (PMID 21831306, 2011). "A clinically important question is what types of cancer would benefit most from ani-Dll4 therapy." (PMID 21923938, 2011). "In summary, Dll4 is expressed in cancer-associated endothelial cells, but not the endothelium adjacent normal colonic mucosa." (PMID 19844231, 2009). "We propose an experimental framework to noninvasively assess Dll4 expression levels in tumors based on the NIR signal intensity time course of perfusion patterns characterized by ICG time kinetics to develop a predictive model to support effective decision making in cancer therapy." (PMID 36900252, 2023). "Thus, while anti-DLL4 may bypass the side effects previously observed with GSI or combined anti-NOTCH1/2 antibodies, chronic DLL4 inhibition as required for optimal anti-cancer activity remains problematic." (PMID 34124039, 2021). "Additionally, Dll4/Notch inhibition has been found to reduce the frequency of cancer stem cells." (PMID 26314892, 2015). "Interestingly, DLL4 expression in other cancers is not always associated with a poor clinical prognosis." (PMID 23898884, 2013). "Differential gene expression and gene ranking analyses revealed that the expression of CD74, HLA-DRA, HLA-DRB1, and FXYD3 was elevated in MHC-II+ cancer cells, whereas the expression of LOXL2 and DLL4 was increased in MHC-II− cancer cells." (PMID 41281745, 2025). "FKBPL-based therapeutic peptide mimetic, AD-01 (preclinical peptide candidate), has showed a potent anti-angiogenic and anti-cancer stem cell effects in cancer via CD44 and DLL4." (PMID 40109359, 2025). "In particular, cancer cells several rows behind the leading edge exhibited upregulated Notch1, Nrf2, and miR-200c while cells at the leading edge expressed ZEB1, Dll4, and Jagged1." (PMID 35480877, 2022). "Therefore, blocking DLL4 in the early stages of cancer development may be risky." (PMID 34944837, 2021). "Only very recently, comparable distinct roles for NOTCH ligands in various cancer types and in connection with certain signaling pathways have been identified, such as for JAG1, DLL1, and DLL4." (PMID 33430387, 2021). "Ligands are also expressed in most human tissues, including cancer tissues: these are the Jagged 1 and 2 proteins (JAG1 and JAG2), and the delta-like ligands (DLL1, DLL3, and DLL4)." (PMID 34944837, 2021). "ABL001 demonstrated more potent anti-angiogenic and anti-cancer effects in vitro and in vivo, as compared to the VEGF-targeting or the DLL4-targeting monoclonal antibodies alone, in various assay systems." (PMID 33383646, 2020).
cancer (continued). "For instance, at the American Association of Cancer Research (AACR) 106th Annual Meeting 2015, dual targeting of delta-like ligand 4 (DLL4) and programmed death 1 (PD1) was demonstrated to be a promising cancer therapy." (PMID 27343550, 2017). "Next, we verified that DLL4 expression affected GCSPC function by regulating activity of the Notch‐1 pathway, driving cancer metastasis and resulting in unfavorable disease outcome." (PMID 27891816, 2017). "We further analyzed the DLL4 mRNA and protein levels in LFS cell lines and cancer cell lines by using RT-PCR and immunoblot." (PMID 27542210, 2016). "DLL4-mediated NOTCH1 signaling represents an essential pathway for vascular development and has emerged as an attractive target for angiogenesis-based cancer therapies." (PMID 21824400, 2011). "Therefore, we proposed that TTN-inactivated cancer cells promoted MCT4 expression and regulated MDSC glycolysis via secreting DLL4." (PMID 41326912, 2025). "As a result, one of the pillars of anti-cancer therapy is based on counteracting pro-angiogenic factors such as Vascular Endothelial Growth Factor A (VEGF-A), angiopoietin 2 (Ang-2) and Delta-like Ligand 4 (DLL4)." (PMID 36432631, 2022). "In non-skeletal organs and malignant tumours, Dll4 acts as a potent inhibitor of vascular growth and sprouting." (PMID 34836954, 2021). "NOTCH2/3 and DLL4 can significantly differentiate non-cancerous samples from cancers and were broadly altered in subgroups." (PMID 34205690, 2021). "In previous studies, ABL001 has demonstrated anti-cancer effects with higher potency in several human cancer xenograft models compared to that shown by the VEGF-targeting antibody (bevacizumab-similar) and the DLL4-targeting monoclonal antibody alone." (PMID 33383646, 2020). "This feed-forward circuit with DLL4, Notch3, MSI-1, NUMB and Notch1 may be relevant for the regulation of Notch during cancer formation." (PMID 29104587, 2017). "The DLL4-positive cancer group had a significantly poorer survival than the DLL4-negative group (p < 0.01)." (PMID 23898884, 2013). "Unlike γ-secretase inhibitors that broadly block all Notch signaling, specific targeting of Dll4 with anti-Dll4 antibodies did not induce overt gastrointestinal toxicity and has thus emerged as an attractive target for anti-angiogenic cancer therapy." (PMID 21923938, 2011). "Endothelial cells adjacent to normal colon mucosa distant from cancer did not express Dll4 protein (0 out of 107)." (PMID 19844231, 2009). "Interestingly, the knock-down of Jagged1 and DLL4 also blocked Notch-induced invasion and migration along with increased E-cadherin and decreased N-cadherin and vimentin protein levels in irradiated MCF7 cancer cells." (PMID 27462787, 2016). "Therefore, DLL4 may provide a strong platform as an immuno-therapeutic target in LFS and cancer patients." (PMID 27542210, 2016). "By contrast, stromal upstream regulators that were not estimated to be paracrine effector genes, such as DLL4, APP, and TGFB1, showed no significant increase in expression levels in KIRC cancer components compared with CCLE or GTEx." (PMID 35079698, 2021). "Present data show that NILCO molecules (Notch1, Notch2, Notch3, Notch4, DLL4, and JAG1) and targets (Survivin, Hey2, IL-1R tI, and OB-R) were expressed in EmCa regardless of ethnicity and cancer type." (PMID 28659656, 2017). "We analyzed DLL4 gene expression and protein level in LFS non-cancerous skin fibroblast cell lines and non-LFS cancer cell lines." (PMID 27542210, 2016).
infection (14 papers, 2009 to 2025). The state of being infected such as from the introduction of a foreign agent such as serum, vaccine, antigenic substance or organism. "Although Ad-lacZ-V5 infection had no overt effects, restoration of ERG expression by Ad-ERG-V5 infection resulted in a significant rescue of both DLL4 expression and vessel outgrowth in ECFAKKO mice." (PMID 35723257, 2022). "In the bone marrow, resolution of infection decreased the amount of DLL4 expressed on the surface of multipotent progenitor cells." (PMID 27933064, 2016). "Our current data indicate that DLL4 expression on APCs influences the T cell immune response during mTB infection." (PMID 27933064, 2016). "The periodic expression of DLL4 during lytic infection may contribute to “topping up” Notch signaling established by JAG1 during latency." (PMID 19816565, 2009). "Notably, the Notch4/DLL4 signaling pathway serves as a central regulator in the infection-mediated apoptosis, as evidenced by E. coli intrauterine infection models showing upregulated Notch4/DLL4 expression and enhanced pulmonary microvascular endothelial cell apoptosis." (PMID 41030317, 2025). "Five (cultured on OP9-Mock for 5 days) or 10 days (cultured on OP9-Mock for 10 days) after co-cultured on OP9-Mock cells following the infection, pro-B cells were cultured again on OP9-Mock (Mock) or OP9-Dll4 (Dll4) stromal cells for 3 days." (PMID 34382935, 2021). "Likewise, Ad-ERG-V5 infection of ECFAKKD and ECFAKY397F mutants restored both ERG and DLL4 levels back to those found in control pups, and also restored the vascular outgrowth phenotypes in these mice." (PMID 35723257, 2022). "On days 4 and 7 of infection, a higher number of all lung phagocytes, excluding monocytes, were DLL4+ rather than Jagged2+." (PMID 35603470, 2022). "Moreover, DLL4 depletion via stable lentivirus KDs has an inhibitory effect on viral replication, affecting late ORF65 protein production, viral load and infection virion production." (PMID 35239998, 2022). "Accordingly, the increased expression of DLL4 and NOTCH3 may provide the stimulus to activate crypt cell proliferation to replace the enterocytes lost to apoptosis early in infection." (PMID 23593167, 2013). "Upon infection of ST cells and organoids (MOI of 1), the expression of NOTCH1 and JAG2 significantly decreased, in contrast to that of DLL4, whose expression increased." (PMID 41272765, 2025).
retinopathy (3 papers, 2016 to 2021). "For example, abnormally high levels of VEGFR signaling were recently shown to drive synchronous oscillations of Dll4 in neighboring EC, underpinning a switch from normal EC communal branching behavior to the pathological vessel expansion associated with human retinopathies." (PMID 31189101, 2019). "Effects of CYP2J2 on Dll4 and Jagged1 expression in hypoxia-induced retinopathy." (PMID 34666595, 2021).
immune diseases (2 papers, 2013 to 2025). "In summary, our findings elucidate the new role of Dll4 in the phenotype and function of DCs and provide a novel approach for manipulating T cell-driven deleterious immune diseases." (PMID 23696838, 2013).
metabolic disease (2 papers, 2019 to 2020). A congenital disorder (due to inherited enzyme abnormality) or acquired (due to failure of a metabolically important organ) disorder resulting from an abnormal metabolic process. "Previous evidence advocates that miR-30 as well as DLL4 blockade may be therapeutically beneficial to reducing severity of metabolic disorders." (PMID 31134094, 2019).
vascular disorder (2 papers, 2019 to 2024). A general term used to describe any disease affecting blood vessels]. "Dll4 mutants also showed coronary vessel hemorrhaging reminiscent of that found in vascular disorders or tumors and indicative of disrupted endothelial integrity." (PMID 31789590, 2019). "DLL4/NOTCH1/PPARγ agonists and/or PI3K/AKT antagonists are attractive therapeutic targets for preventing or even possibly reversing progressive pathologic vasculopathy in PAH." (PMID 38903104, 2024).
DLL4 also shares sentences with these, for which no sentence is quoted: Adams-Oliver syndrome (5 papers); cardiovascular disease (3); acute T-cell lymphoblastic leukemia (2); allergic disease (2); colorectal (2); cyst (2); experimental autoimmune encephalomyelitis (2); lung adenocarcinoma (2); lupus nephritis (2); metabolic syndrome (2); metastasis (2); metastatic disease (2); Salmonella Infections (2); 22q11.2 deletion syndrome (1); adenocarcinoma (1); Adrenocortical Carcinoma (1); Alagille syndrome type 1 (1); Allergy (1); angiosarcoma (1); aplasia cutis congenita (1); arteriovenous malformations (1); autoimmune uveitis (1); Beckwith-Wiedemann syndrome (1); brain cancer (1); brain ischemia (1); cardiomyopathy (1); chronic kidney disease (1); congestive heart failure (1); craniopharyngioma (1); demyelinating disease (1).
A further 45 diseases each share a sentence with DLL4 in 1 paper.